INS (insulin)
Diseases named in the same sentence as INS in open-access papers (continued):
Sharing a sentence is not in itself a finding about the gene and the disease.
cardiovascular disease (continued). "However, glycemic control and insulin treatment require more motivation and patient education than other aspects of cardiovascular disease risk factor control." (PMID 16716235, 2006). "Since adEV could potentially be involved with proteins and genetic materials that could participate in cytokine production or insulin signaling pathway, especially in terms of glucose and lipid regulation, they have been implicated in the development of cardiovascular disease." (PMID 39010858, 2024). "Concretely, the positive effects of MD on blood pressure, insulin sensitivity, lipid profiles, lipoprotein particles, inflammation, oxidative stress, and carotid atherosclerosis were supported by significant improvements in traditional and emerging cardiovascular disease (CVD) risk factors." (PMID 38541047, 2024). "However excessive insulin therapy increases IR and may expose the patients to risk of cardiovascular disease." (PMID 39252700, 2024). "Furthermore, the non-insulin-based indices’ capacity to reflect many dimensions of IR, including the severity of IR and its correlation with cardiovascular disease risk, contributes to a more comprehensive evaluation of the overall health status of diabetic patients." (PMID 39720248, 2024). "As insulin sensitivity in adolescents with T1D has been shown to be inversely associated with cardiovascular disease risk factors, studies focused on IR may play a key role in identifying potential biomarkers for future diabetic complications and may provide therapeutic targets." (PMID 37715520, 2023). "In studies comparing VLBW adults with normal birth weight controls, VLBW adults had lower insulin sensitivity and higher fasting concentrations of triglycerides in chylomicrons, very-low-density lipoproteins, and high-density lipoproteins, increasing the risk of cardiovascular disorders." (PMID 37892346, 2023). "Interestingly, deficiencies in IGF-1 or growth hormone are associated with an increased risk of cardiovascular disease, yet centenarians tend to exhibit improved insulin sensitivity, low IGF-1 levels, and specific mutations in the insulin receptor that are associated with extreme longevity." (PMID 38203522, 2023). "Studies have reported that serum leptin and adiponectin concentrations increase and insulin sensitivity and endothelial function improve after infliximab treatment, which affect inflammation burden and plaque vulnerability and reduce the risk of cardiovascular disease." (PMID 35187113, 2021). "Of note that higher intake of CGA may elevate homocysteine levels, a risk factor for cardiovascular disease, and stimulate the release of adrenaline generating several effects on the cardiovascular system including increased blood pressure and reduced insulin sensitivity." (PMID 32665012, 2020). "Specifically, studies demonstrated that concurrent exercise and metformin administration may blunt the acute effects of a single exercise session on insulin sensitivity and attenuate the chronic effects of exercise training on insulin sensitivity and some risk factors of cardiovascular diseases." (PMID 29785399, 2018). "In addition, insulin induces oxidative stress, leading to free-radical damage that impairs the function of endothelial cells, and also acts like a growth factor that thickens blood vessels and increases the risk of cardiovascular diseases." (PMID 29457038, 2017). "Diabetic ketoacidosis (p = 0.043), cardiovascular diseases (p = 0.005), acute exacerbation of bronchial asthma (p = 0.010), and the use of corticosteroids (p = 0.037) and loop diuretics (p = 0.016) were significantly associated with the type of insulin regimen used." (PMID 25181406, 2014). "Therefore, the aim of the present study was to investigate whether insulin glargine was able to reduce the risk of cardiovascular events and improve β-cell function and insulin sensitivity in T2D patients with a high risk for cardiovascular disease." (PMID 24944613, 2014).
cardiovascular disease (continued). "However, few studies have been performed investigating whether basal insulin therapy decreases cardiovascular events in patients with early T2D at a high risk for cardiovascular disease." (PMID 24944613, 2014). "The role of mTOR and cross-talk with inflammatory and sympathetic systems and insulin signaling are very new and interesting observations and deserve further study to understand the molecular pathophysiology responsible for the increased cardiovascular disease associated with MetS." (PMID 20809949, 2010). "Omega-3 fatty acids, widely studied in metabolic and cardiovascular diseases, often require high doses and show variable outcomes, including paradoxical reductions in insulin sensitivity in specific populations." (PMID 41002745, 2025). "In this study, the interaction between GRS and PDI was performed on some predictive factors of cardiovascular diseases, such as C-reactive protein, plasminogen activator inhibitor 1, and insulin." (PMID 40628909, 2025). "Insulin-treated participants were also more likely to have a history of cardiovascular disease, a higher baseline body mass index, lower eGFR and higher levels of albuminuria." (PMID 40036884, 2025). "T2DM is a major risk factor for cardiovascular diseases, including ACS, and leptin is known to influence insulin sensitivity and glucose metabolism." (PMID 40362168, 2025). "Changes in sex hormones, growth, insulin sensitivity, and inflammatory responses affect cardiovascular disease development in obese children." (PMID 40923080, 2025). "C-peptide, a marker of endogenous insulin production, has been widely studied for its protective effects against microvascular damage and cardiovascular disease in individuals with T2D." (PMID 41153704, 2025). "Excessive fatty acids (FAs) are stored after consumption, and various lipids act as signaling molecules in insulin resistance and inflammatory pathways, thereby influencing cardiovascular disease onset." (PMID 41195417, 2025). "Visceral fat is known to increase triglyceride production, impair insulin action, and promote systemic inflammation, all of which play a role in the onset of cardiovascular disease and various metabolic conditions." (PMID 40342979, 2025). "Insulin resistance (IR) is primarily characterized by reduced insulin sensitivity, which contributes to vascular stiffening and the development of cardiovascular disease." (PMID 41356015, 2025). "This dietary approach not only promotes a healthier lipid profile but also enhances insulin sensitivity, reduces systemic inflammation, and aids in the prevention of cardiovascular diseases." (PMID 39860021, 2025). "Interorgan signaling pathways participate in lipid metabolism, blood pressure regulation, insulin sensitivity, and inflammation, and their dysregulation is now recognized as a key driver of cardiovascular disease (CVD)." (PMID 40403107, 2025). "Historically, the pharmacologic therapy of cardiovascular disease has centered around blood pressure control, insulin and cholesterol management, the inhibition of the renin–angiotensin system, and catecholamine blockade." (PMID 40558547, 2025). "Prior data collected between 2010 and 2018 showed that GLP-1RA had been prescribed for patients with progressively more advanced disease stage, frequent use of insulin and high prevalence of cardiovascular disease." (PMID 38369592, 2024). "Regular physical activity can positively impact preventing and managing diabetes by enhancing glucose and insulin metabolism and decreasing the likelihood of cardiovascular disease." (PMID 38547044, 2024). "Sand rice has a balanced and comprehensive nutritional value and is rich in polyunsaturated fatty acids, which have significant potential in treating cardiovascular diseases, insulin sensitivity, and immunity." (PMID 39479695, 2024). "Regular exercise plays a crucial role in reducing the likelihood of cardiovascular disease by enhancing glucose and insulin metabolism." (PMID 38547044, 2024).
cardiovascular disease (continued). "This pathway’s role in adipogenesis and insulin sensitivity also links it to obesity-related diseases like T2D and cardiovascular disorders." (PMID 39125390, 2024). "TNF-α interferes with insulin pathways, fostering a state of chronic inflammation that can lead to complications such as cardiovascular disease." (PMID 39840100, 2024). "It should also be noted that higher ketone levels are detrimental to vascular health, but moderate ketone levels protect against cardiovascular disease by improving insulin sensitivity and reducing inflammation in certain conditions." (PMID 39796562, 2024). "Benefits of exercise include increased insulin sensitivity, improved glycaemic control, and prevention of cardiovascular disease." (PMID 38921462, 2024). "Previous studies with injectable GLP-1RA indicate their use in later stages of T2D, often in patients with a higher prevalence of cardiovascular disease and concurrent insulin therapy." (PMID 38369592, 2024). "Compared to DPP4i users, those using SGLT2i and GLP1a were more likely to be of younger age; were less likely to have cardiovascular disease; had higher BMI and HbA1c levels; and were more likely to have insulin use." (PMID 38993538, 2024). "Proximal insulin signaling impairment is a critical factor contributing to metabolic and cardiovascular disorders." (PMID 39125938, 2024). "Based on our knowledge, up to now, there has not been a report on the effect of zinc nanoparticles on obesity-induced cardiovascular disease concerning iron overload, blood pressure, insulin resistance, adipocyte hormones, and inflammatory markers." (PMID 37749096, 2023). "Such chronic environmental stressors that shift the CNS clock circuit temporal organization to amplify and lock the individual in the seasonal insulin-resistant neurometabolic physiology for years on end can lead to cardiometabolic and cardiovascular disease." (PMID 37686060, 2023). "In case study 1, the primary cardiovascular disease nodes were connected to first neighbour nodes representing cholesterol, blood glucose, or insulin dysregulation traits." (PMID 37610350, 2023). "The relationship between biotin and glucose/insulin metabolism further implicates biotin as an essential nutrient for the prevention of cardiovascular diseases." (PMID 37551230, 2023). "The association of the android-to-gynoid ratio with metabolic and cardiovascular diseases has been reported, which can be explained by the crucial role of insulin in metabolism." (PMID 37833665, 2023). "Further investigation is warranted to validate the beneficial effects of a DPP‐4i on cardiovascular disease when it is used in combination with insulin in patients with advanced T2DM." (PMID 37528628, 2023). "In the SURPASS-4 study, which enrolled patients with established cardiovascular disease, weight-loss independent effects explained 33% to 57% of difference in SBP change between tirzepatide and insulin glargine groups." (PMID 36964557, 2023). "Overexpression of some PRX isoforms affects susceptibility to glucose intolerance and cardiovascular disease; for example, PRX2 is implicated in skeletal muscle redox messaging and insulin sensitivity." (PMID 37812879, 2023). "Subcutaneous fat differs from visceral fat in some ways, including insulin sensitivity, lipolysis activity, and adipocytokines production, all of which contribute to the development of cardiovascular disease." (PMID 38144570, 2023). "In modern man, these chronic “stress” signals “lock” the CNS-clock control of metabolism in the insulin-resistant state chronically (i.e., for years), which over time potentiates insulin resistance syndrome and cardiovascular disease." (PMID 37686060, 2023). "This was the case where the type of regimen such as being on metformin, insulin, and combination of insulin and oral-antidiabetic drugs, as well as having cardiovascular disease were found to influence good glycaemic control." (PMID 37315063, 2023).
cardiovascular disease (continued). "ZnONPs are convenient in treating cardiovascular disease in obese rats via reduced blood pressure, oxidative stress, cardiac iron accumulation, insulin resistance, and inflammatory markers." (PMID 37749096, 2023). "The multifaceted functions of FGF21 in insulin sensitisation, lipid metabolism and inflammatory modulation collectively assist in its resistance to the progression of cardiovascular disease." (PMID 37822930, 2023). "Although C-peptide was recognized as an important marker insulin secretion in the literature, its bioactive effects on cardiovascular disease and complications expose attracting attention of researchers in recent years." (PMID 36192784, 2022). "We and others have previously shown the importance of insulin sensitivity as a primary determinate of cardiovascular disease development in T1DM." (PMID 36083870, 2022). "IGF-1 plays an important role in muscle development and insulin sensitivity, and changes in IGF-1 are correlated with cardiovascular disease risk and mortality." (PMID 34936049, 2022). "Nevertheless, much research indicates that exercise has positive effects, such as lower cardiovascular disease prevalence, lipid improvement, and insulin sensitivity." (PMID 36292410, 2022). "All participants were diagnosed with T2D, 49% (n = 65) were on insulin treatment, 16% (n = 22) were diagnosed with cardiovascular disease and 58% (n = 77) received statin treatment." (PMID 36577984, 2022). "Sirt4 also has an important role in insulin secretion, fatty acid oxidation, amino acid metabolism, ATP homeostasis, and cardiovascular diseases." (PMID 36160705, 2022). "This improves the condition of blood vessels, insulin resistance, and lipid disorders, which in turn leads to beneficial effects on many diseases, including cardiovascular diseases." (PMID 36235812, 2022). "In a study that investigated the effect of a plant-based diet on cardiovascular disease, it turned out to be positive because it lowered blood pressure, HR, and insulin levels." (PMID 36558540, 2022). "Exercise, optimally with an appropriate diet, is known to improve arteriolar dilation, increase insulin sensitivity and reduce the systemic low-grade inflammation that accompanies cardiovascular disease." (PMID 35624760, 2022). "Late chronotype (LC) correlates with reduced metabolic insulin sensitivity and cardiovascular disease." (PMID 36301720, 2022). "The complex pathophysiology stems from coexisting cardiovascular disease and complications of impaired tissue sensitivity to insulin." (PMID 34692349, 2021). "Loss of CLC-3 leads to a variety of defects including hippocampal degeneration, impaired insulin secretion, and cardiovascular disease." (PMID 34910516, 2021). "From the analysis, having low education (only elementary or JHS), being morbidly obese, being on insulin therapy, having cardiovascular disease, and taking coffee seldom or once per day significantly affected one’s glycaemic control." (PMID 34936668, 2021). "Apelin is responsible for, i.a., cardiovascular function and insulin secretion, and its functional disorders are associated with DM2 and cardiovascular system diseases." (PMID 34684585, 2021). "The main exclusion criteria were: smoking, exogenous insulin, beta blockers or arrythmia, and cardiovascular disease." (PMID 33999947, 2021). "This process is considered among the most important initial step of atherosclerosis towards cardiovascular diseases, and it is a fingerprint of obese-insulin resistant-diabetic subjects." (PMID 33668627, 2021). "This can lead to a reduction in insulin sensitivity, increase the secretion of proinflammatory cytokines in adipose tissue, and promote the development of cardiovascular diseases." (PMID 34440918, 2021). "Further, associations between reduction in serum omega-6/omega-3 and cholesterol-lowering and improvements in insulin sensitivity are observed in patients with cardiovascular disease following statin treatment." (PMID 32155696, 2020).
cardiovascular disease (continued). "The prevalence of single dispensing in cardiovascular disease and insulin is high, and further studies are required to examine this in detail." (PMID 32408626, 2020). "SGLT2 inhibitors plus insulin therapy significantly improves glycemic control and reduce total daily insulin dose, body weight, and the risks of cardiovascular disease." (PMID 32351447, 2020). "Suprapatellar amputation correlated with the presence of cardiovascular disease, insulin use, and low primary healthcare attendance with specific guidance." (PMID 32715137, 2020). "Multi-LAB treatment significantly increased serum concentrations of stearic acid and oleic acid, which demonstrated the potential of this multi-LAB mixture for preventing cardiovascular diseases and increasing insulin sensitivity." (PMID 32824501, 2020). "T1D patients are younger, more active and more prone to PA, which can enhance their insulin sensitivity, glycaemic control, lipid profile, antioxidant defences and renal function and also decrease blood pressure and cardiovascular diseases." (PMID 33467285, 2020). "ST treatment significantly decreased body weight and fat accumulation in HFD-induced obese mice, while reducing insulin and factors related to cardiovascular diseases (triglyceride and total cholesterol) in serum." (PMID 33138053, 2020). "Improving gut health can, in turn, result in reduced inflammation, cardiovascular disease prevention, better insulin sensitivity, improvement of blood lipid levels, more satiety, obesity control, and colorectal cancer." (PMID 32396556, 2020). "History of cardiovascular disease, BMI, waist circumference, statin use, hsCRP, glucose, insulin, HbA1c, and C-peptide all increased with the upper quartiles of HOMA-IR." (PMID 30786864, 2019). "In the case of APOE, APOE ε2 isoform decrease the risk of cardiovascular disease and APOE ε4 isoform limits longevity and FOXO3 is linked to insulin/insulin-like growth factor 1 (IGF1) signaling." (PMID 30926763, 2019). "White adipose browning can increase energy consumption, reduce weight, increase insulin sensitivity, and improve glucose tolerance and cardiovascular disease." (PMID 31022919, 2019). "These inflammatory mediators secreted by the adipose tissue can trigger different metabolic abnormalities, impairing insulin signaling and inducing oxidative stress, leading to systemic insulin resistance and cardiovascular disease." (PMID 31801236, 2019). "The impairment of β-cell function decreases the glucose-induced insulin secretion, resulting in an increased glycemic level in T2DM patients, which significantly increases the risk of cardiovascular disease." (PMID 30987625, 2019). "This has relevant implications for reducing meta-inflammation, and, consequently, resistance to insulin action and the risk of DM2 and cardiovascular disease in obese individuals." (PMID 29601492, 2018). "The visceral adiposity index (VAI), a valuable indicator of visceral adiposity function and insulin sensitivity, has been demonstrated to be an independent predictor of cardiovascular disease and an easy tool to show a condition of cardiometabolic risk." (PMID 30093885, 2018). "These benefits were evidenced by the regulation in metabolic and inflammatory pathways, cardiovascular diseases, as well as in glucose homeostasis and insulin sensitivity." (PMID 29652940, 2018). "Impaired insulin signaling and high glucose are strongly interlinked with cardiovascular disease (CVD) in the setting of T2D." (PMID 28891325, 2018). "Many studies report the benefits promoted by exercise training in cardiovascular diseases by reducing blood pressure, glucose levels, and improving insulin signaling and lipid metabolism." (PMID 30445764, 2018). "It is known that alterations in lipid profiles, insulin, and HOMA-IR during childhood are risk factors for cardiovascular diseases and generally carry over into adulthood." (PMID 29402762, 2018).